MYC (MYC proto-oncogene, bHLH transcription factor)
Diseases named in the same sentence as MYC in open-access papers (continued):
Sharing a sentence is not in itself a finding about the gene and the disease.
medulloblastoma (continued). "Glucose was the main carbon source for glutamate synthesis through the TCA cycle in high MYC amplified medulloblastoma." (PMID 35267619, 2022). "We used uniformly labeled glutamine (13C5, 15N2) to understand how high MYC medulloblastoma in different environments metabolized glutamine." (PMID 35267619, 2022). "Recently, an ex vivo model of medulloblastoma was developed by overexpression of Otx2/c-MYC in cerebellar organoids which showed a disease-specific DNA methylation signature." (PMID 35978801, 2022). "We found similar changes in MED211 high MYC amplified medulloblastoma in flank xenograft tumors compared to MED211 cells in culture." (PMID 35267619, 2022). "In another study, the role of the pro-autophagy factor AMBRA1 in regulating medulloblastoma was identified showing that AMBRA1 expression depends on c-MYC levels and is correlated with poor prognosis in group 3 patients." (PMID 36197606, 2022). "A subset of group 3 medulloblastomas have amplification of MYC, which portends even worse prognosis." (PMID 35266242, 2022). "HDAC inhibitors repress EGFR/EGFRvIII expression inducing the expression of FOXO1—a tumor suppressor—in MYC-driven medulloblastoma cells." (PMID 35785151, 2022). "The differences in metabolic profile between the orthotopic, flank and in vitro settings reflect the plasticity of D425-MED and MED211 MYC amplified medulloblastoma." (PMID 35267619, 2022). "Especially MYC and E2F associated proteins showed a significantly higher abundance in ATRT and medulloblastoma." (PMID 35725563, 2022). "The metabolism of MYC-amplified medulloblastoma cancer cells is different in vitro compared to in vivo." (PMID 35267619, 2022). "The high degree of concordance between MED211 and D425MED in all analyses suggests reliance on common metabolic pathways in MYC-amplified medulloblastoma." (PMID 35267619, 2022). "Our metabolic analysis of MYC-amplified medulloblastoma revealed upregulation in the metabolism of nucleotides, glutathione, the hexosamine biosynthetic pathway, the urea cycle and amino acids compared to normal brain." (PMID 35267619, 2022). "We identified multiple metabolites that are altered in orthotopic MYC-amplified medulloblastoma xenografts compared to normal brain and showed in a large clinical dataset that the mRNAs for key enzymes in these pathways are upregulated." (PMID 35267619, 2022). "We therefore performed PCA comparing known metabolites of D425MED and MED211 MYC—amplified medulloblastoma in three different environments: in vitro, flank xenograft and orthotopic xenograft tumors growing in the cerebellum." (PMID 35267619, 2022). "We identified significant differences in glucose and glutamine metabolism in high MYC medulloblastoma comparing in vitro, flank xenografts and orthotopic xenograft medulloblastoma models." (PMID 35267619, 2022). "Our findings were consistent with recently reported proteomics data in MYC-amplified medulloblastoma, showing upregulation of the glutathione biosynthetic pathway compared to non-MYC-amplified medulloblastoma and normal brain." (PMID 35267619, 2022). "The expression of GABRA5, which encodes the α 5-GABAA receptor, has a synthetic lethal role in MYC-driven medulloblastoma." (PMID 36105089, 2022). "FBXW7 acts as a tumor suppressor in MYC-amplified medulloblastoma: the overexpression of FBXW7 induces cell apoptosis, suppresses cell proliferation, and improves the survival of orthotopic xenograft bearing mice." (PMID 33494392, 2021).
medulloblastoma (continued). "The medulloblastoma subgroup 3 (MYC amplified subgroup) was successfully modeled in cerebellar organoids by combination of MYC and OTX2 or GFI1 overexpression." (PMID 33718380, 2021). "These cell lines have been validated as accurate representations of MYC-amplified Group 3 medulloblastoma using DNA methylation array and C11orf95 ependymoma using PCR." (PMID 33477420, 2021). "The PVT1–MYC fusion is the most frequently detected fusion that is identified in 60% of MYC-amplified group 3 medulloblastomas (12 out of 20 samples)." (PMID 34830991, 2021). "We recently performed a drug screen that identified kinase inhibitors of the DNA damage response (DDR) pathway and cell cycle machinery as potent agents against MYC-amplified Group 3 medulloblastoma in combination with chemotherapy." (PMID 33996894, 2021). "We previously demonstrated that PLK1 is highly expressed in MYC-driven medulloblastoma and that the inhibition of PLK1 with BI2536 suppresses tumor cell growth." (PMID 33494392, 2021). "Because non-MYCN-amplified NB cell lines, including SK-N-AS, express MYC which is a target for combined BET/mTOR in medulloblastoma cells." (PMID 34565342, 2021). "Beyond NB, this therapeutic approach can be of broader relevance for therapy of MYC/MYCN-addicted cancers, as we have previously shown a synergistic antitumor efficacy of BET/mTOR inhibitors in MYC-driven medulloblastoma." (PMID 34565342, 2021). "Human cerebellar organoids derived from iPS cells electroporated with Otx2/c-MYC induced Group 3 medulloblastoma." (PMID 33869004, 2021). "We tested inhibition of the DDR pathway in combination with radiotherapy in MYC-amplified Group 3 medulloblastoma." (PMID 33996894, 2021). "Group 3 cell lines expressed lower levels of the FBXW7 protein and higher levels of the PLK1 and MYC proteins compared with the SHH group or normal cerebellum, further confirming the inverse relationship of FBXW7 and MYC/PLK1 in medulloblastoma." (PMID 33494392, 2021). "Here we present the first collection of lncRNAs dependent on the activity of the MYC oncogene, the major driver gene of Group 3 Medulloblastoma." (PMID 34359754, 2021). "Another combination therapy using CDK2 inhibitors with bromodomain-containing protein 4 (BRD4) inhibitors in MYC amplified medulloblastoma resulted in MYC suppression and promoted apoptosis." (PMID 33805800, 2021). "Additional targets of FBXW7, including AURORA A MCL-1, and Cyclin E, were also downregulated in response to PCM-075 in MB cells, implying FBXW7 is an upstream regulator of c-MYC in medulloblastoma." (PMID 33494392, 2021). "Specifically, these models represent MYC-amplified Group 3 medulloblastoma and C11orf95 fusion-positive ependymoma." (PMID 33477420, 2021). "Although most SHH medulloblastomas highly express MYCN, the few SHH (or SHH-like) medulloblastoma cell lines (UW-228-2 and DAOY) prominently express only MYC, similar to most Group 3 medulloblastomas." (PMID 33425720, 2020). "Further, we have extended the co-expression correlation analysis to one of the MYC amplified cancer, Medulloblastoma (GEO ID: GSE50765)." (PMID 31932624, 2020). "The expression of miR-193a inhibited growth, tumorigenicity, and increased radiation sensitivity of MYC amplified/overexpressing Group 3 medulloblastoma cells." (PMID 32410663, 2020). "MiR-193a, therefore, has therapeutic potential for the treatment of not only the Group 3 medulloblastomas but possibly other MYC overexpressing aggressive cancers as well." (PMID 32410663, 2020). "The D425 cell line is categorized as a group 3 medulloblastoma, with high MYC proto-oncogene amplification." (PMID 32443610, 2020). "Restoration of miR-193a expression in the MYC amplified Group 3 medulloblastoma cells resulted in inhibition of growth, tumorigenicity, and an increase in radiation sensitivity." (PMID 32410663, 2020).
medulloblastoma (continued). "Among the four molecular subgroups of medulloblastomas, Group 3 tumors carrying MYC /MYCN amplification are the most aggressive tumors with the worst prognosis." (PMID 32410663, 2020). "The extension of the analysis was done on MYC proficient and MYC deficient embryonic fibroblast cell lines, TGR1 and HO15, and in one of the MYC amplified cancer types, Medulloblastoma." (PMID 31932624, 2020). "MiR-193a not only targeted MAX but several proliferation-related genes like CCND1, E2F1, STMN1, and chromatin modifier gene KMT2A that brought about widespread repression of gene expression in the MYC amplified Group 3 medulloblastoma cells." (PMID 32410663, 2020). "In this study, we report the clinical and mutational profiles of 99 adult medulloblastomas, investigated for molecular group, coding mutations, TERT promoter mutations, MYC and MYCN amplifications, and survival outcome." (PMID 33172502, 2020). "Knockdown of PRMT5 using siRNA in MYC-driven medulloblastoma cells significantly decreased cell growth and MYC expression." (PMID 31694585, 2019). "Taken together, these results suggest that inhibiting the specific interaction of PRMT5 with MYC arrests medulloblastoma cell growth and favors apoptosis in MYC-dependent tumors." (PMID 31694585, 2019). "MYC-driven medulloblastomas have a particularly poor prognosis, as they are commonly metastatic and resistant to standard therapy." (PMID 31757062, 2019). "We also validated these ORFs as rescue genes in other patient-derived MYC-driven medulloblastoma cell lines: D341 and two that are passaged in serum-free conditions: CHLA01 and the recently generated cell line MB002." (PMID 31160565, 2019). "We and others have shown BET-bromodomain inhibition (BETi) to be a potential therapeutic strategy to target MYC-driven medulloblastomas and other cancers." (PMID 31160565, 2019). "Together, these results suggest that PRMT5 physically interacts with and stabilizes MYC in medulloblastoma cells at the post-translation level." (PMID 31694585, 2019). "The observation of physical interaction between PRMT5 and MYC indicates a potential functional role of this novel protein complex in medulloblastoma." (PMID 31694585, 2019). "To further authenticate this correlation at the protein level, we examined the expression of PRMT5 and MYC by immunohistochemistry in Group 3 medulloblastoma tumor samples (n = 6) compared to normal pediatric cerebellum (n = 4)." (PMID 31694585, 2019). "We next determined the ability of EPZ015666 to induce apoptosis in a representative MYC-amplified medulloblastoma cell line HD-MB03." (PMID 31694585, 2019). "HDAC inhibitors have been reported to inhibit growth of medulloblastoma cells particularly that of MYC-driven Group 3 cell lines." (PMID 30944042, 2019). "To investigate the role of PRMT5 on MYC function, we determined the effect of short-interfering RNA (siRNA)-mediated knockdown of PRMT5 on MYC expression and cell survival in MYC-amplified medulloblastoma cell lines." (PMID 31694585, 2019). "We observed significantly higher expression of PRMT5 in Group 3 (MYC-driven) medulloblastoma compared to other 3 subgroups." (PMID 31694585, 2019). "In summary, we have demonstrated for the first time that PRMT5 is a critical regulator of MYC expression in MYC-amplified medulloblastomas." (PMID 31694585, 2019). "To further understand how MYC fine-tunes lysosomal biogenesis, we tested a set of mouse group 3 medulloblastoma cell lines overexpressing Myc40,44." (PMID 31399583, 2019).
medulloblastoma (continued). "We observed that PRMT5 protein levels were significantly (p < 0.01) higher in MYC-driven medulloblastoma cell lines compared to non–MYC medulloblastoma cell lines and normal human cerebellum cells." (PMID 31694585, 2019). "In the context of therapeutics, we observed dose-dependent efficacy of PRMT5 inhibitor EPZ015666 in suppressing cell growth and inducing apoptosis in MYC-driven medulloblastoma cells." (PMID 31694585, 2019). "We analyzed GABR and MYC expression across all subgroups in 763 resected primary medulloblastoma tumors (Online Resource 1, 2)." (PMID 30725256, 2019). "Results from this analysis showed that high expression of PRMT5 was strongly correlated (R-value = 0.531; p-value = 2.51e-05) with high MYC in Group 3 medulloblastoma." (PMID 31694585, 2019). "Tumor suppressive effect of miR-204 in the MYC amplified Group 3 cell lines is remarkable since other microRNAs downregulated in medulloblastoma like miR-206 for instance, fail to inhibit tumorigenicity of these cell lines." (PMID 30944042, 2019). "Together, the results of co-immunoprecipitation and co-localization of MYC and PRMT5 suggest that endogenous PRMT5 forms a complex with MYC in medulloblastoma cells harboring MYC amplification." (PMID 31694585, 2019). "To further test the link between autophagy and MYC activation, we also interrogated Myc-ChIP-seq binding datasets from group 3 mouse medulloblastoma and found that the promoters of several autophagy genes were indeed occupied by Myc." (PMID 31399583, 2019). "MYC-driven medulloblastomas have high metastatic potential and are often resistant to even multimodal treatments." (PMID 31694585, 2019). "Brd4 controls expression of the medulloblastoma essential gene MYC in G3 medulloblastomas, which have poor prognosis as well as GLI1 and GLI2 levels in Sonic hedgehog (SHH)-driven medulloblastomas, which have intermediate prognosis." (PMID 31292434, 2019). "To further support of association between PRMT5 and MYC, we examined co-localization of these two proteins in HD-MB03 cells and a tumor specimen of a Group 3 medulloblastoma patient, using immunofluorescence-coupled with confocal microscopy." (PMID 31694585, 2019). "Using MYC-driven medulloblastoma cells, we examined the physical interaction between PRMT5 and MYC by co-immunoprecipitation and co-localization experiments." (PMID 31694585, 2019). "MYC-driven group 3 medulloblastoma is an aggressive pediatric brain tumor that is refractory to intensive multimodal therapy." (PMID 31160565, 2019). "Further, we showed that knockdown of PRMT5 suppressed medulloblastoma cell growth by inhibiting MYC expression, suggesting a functional role of PRMT5-MYC interaction in medulloblastoma tumorigenesis." (PMID 31694585, 2019). "Consistently, our western blot results further confirmed strongly higher expression of MYC protein in these two cell lines compared to other medulloblastoma lines." (PMID 31694585, 2019). "We found that the protein levels of PRMT5 and MYC were significantly (p = 0.004) higher with more than 75% staining in Group 3 medulloblastoma samples than normal pediatric cerebellum tissues." (PMID 31694585, 2019). "Our results using a PRMT5 inhibitor EPZ015666 highlight the PRMT5-MYC oncogenic axis a viable therapeutic approach for MYC-driven medulloblastoma." (PMID 31694585, 2019). "We conclude that BETi consistently suppresses essential genes in sensitive MYC-amplified medulloblastoma cells, and that these genes consistently belong to cell cycle, DNA replication, and RNA processing pathways." (PMID 31160565, 2019).
medulloblastoma (continued). "Our expression findings confirm that high levels of PRMT5 not only mirror MYC expression in the most aggressive medulloblastomas but also inversely correlate with poor outcomes in patients." (PMID 31694585, 2019). "Given the role of PRMT5 in MYC-driven medulloblastoma cells, we further tested the therapeutic potential of targeting PRMT5 using a selective small molecule inhibitor, EPZ015666, against medulloblastoma cell lines." (PMID 31694585, 2019). "We used two cell lines D-341 and HD-MB03 in this study as both lines have previously been reported as well-established Group 3 medulloblastoma cell lines with high MYC expression." (PMID 31694585, 2019). "We characterized the extent and uniformity of transcriptional effects of BETi in medulloblastoma models through expression profiling of four MYC-driven medulloblastoma cell lines treated with the BET-bromodomain inhibitor JQ1, relative to vehicle controls." (PMID 31160565, 2019). "Here, we report the role of PRMT5 as a novel regulator of MYC and implicate PRMT5 as a potential therapeutic target in MYC-driven medulloblastoma." (PMID 31694585, 2019). "Group 3 medulloblastoma often exhibits MYC amplification or overexpression and has the worst prognosis of the 4 medulloblastoma subgroups with < 50% survival." (PMID 31694585, 2019). "We next analyzed the correlation between PRMT5 and MYC mRNA expression across medulloblastoma subgroups using Pfister (n = 223) cohort at the R2 genomic analysis platform." (PMID 31694585, 2019). "We not only observed intensely high expression of PRMT5 and MYC protein in Group 3 medulloblastoma but also, a positive correlation with their predominantly nuclear co-expression." (PMID 31694585, 2019). "While amplification of MYC defines Group 3 medulloblastomas and confers poor prognosis, such MYC amplification occurs in less than a quarter of Group 3 tumors, with a heterogenous set of other molecular mechanisms occurring in the remainder." (PMID 31554835, 2019). "Our MTT results clearly demonstrated that EPZ015666 significantly induced the dose-dependent growth inhibition of all MYC-driven medulloblastoma cell lines at low micromolar potency with IC50 of ~ 1.5–2.5 μM." (PMID 31694585, 2019). "This analysis carried out on a large number of medulloblastomas showed frequent MYC amplifications in Group 3 and WNT medulloblastomas; in contrast, MYCN amplifications were frequent in SHH and Group 4 tumors." (PMID 30279357, 2018). "The administration of JQ1, a potent inhibitor of BET bromodomain proteins resulted in reduced cell proliferation and markedly enhanced apoptosis in in vitro models of MYC-amplified medulloblastomas and prolonged survival in xenograft models." (PMID 30279357, 2018). "Gene amplifications are rare in medulloblastomas, but when they occur very frequently concern either the MYC or the MYCN oncogenes." (PMID 30279357, 2018). "BRD4 facilitates MYC-mediated transcriptional activation and as such has been explored as a potential therapeutic target in MYC driven medulloblastoma." (PMID 29880060, 2018). "MYC-driven Group 3 (G3) medulloblastoma (MB) is the most aggressive of four molecular subgroups classified by transcriptome, genomic landscape and clinical outcomes." (PMID 29880921, 2018). "d) Expression level of HMGA1 is highly correlated with the expression of the oncogene MYC in Group 3 Medulloblastoma." (PMID 29880060, 2018). "A recent study of drug screening provided evidence that histone deacetylase inhibitors (HDACIs) are potent inhibitors of MYC-driven medulloblastomas." (PMID 30279357, 2018). "Target genes of MYC/MIZ1 are repressed in human G3 medulloblastomas, but not in other subgroups; in animal models, genetic disruption of the MYC/MIZ1 interaction inhibited G3 medulloblastoma development." (PMID 30279357, 2018).